IFNG (interferon gamma)
Diseases named in the same sentence as IFNG in open-access papers (continued):
Sharing a sentence is not in itself a finding about the gene and the disease.
parasitemia (continued). "Mouse studies demonstrate that the frequency of γδ T cells is significantly increased during malaria infection and they provide protective immunity via interferon gamma (IFN-γ) production and control of parasitemia." (PMID 28615061, 2017). "Our findings identify Blimp-1-dependent IL-10 produced by Tr1 cells as a critical regulator of IFNγ-dependent, TNF-mediated tissue damage in the spleen in parasitic infections." (PMID 26765224, 2016). "Our data cannot support the notion that the reduced parasitemia was mediated by CD8+ T cells, because the numbers of IFNγ-producing CD8+ T cells at day 7 post primary vaccination and at day 7 post secondary vaccination were similar." (PMID 25115805, 2014). "The H-2Kb-restricted anti-VNHRFTLV cytotoxic and IFNγ-secreting CD8+ T-cells were first detected before the peak of parasitemia at 15 dpi and reached a maximum level at the peak of parasitemia and heart parasitism (42–45 dpi)." (PMID 22532799, 2012). "Mechanistic studies demonstrated that CD4+ T-cells (but not CD8+ T-cells), and Th1 and Th2 cytokines (interferon gamma and tumor necrosis factor, IL-10) were critical in controlling parasitemia and survival following challenge." (PMID 37962347, 2023). "Skin-resident, IFNγ-producing CD4+ memory T cells protect against Leishmania major re-infection by recruiting circulating T cells and inflammatory monocytes to the site of re-infection, leading to efficient control of parasitic infections." (PMID 29085376, 2017). "While IL10 can be produced by various cell populations, including B cells, monocytes, NK cells, Th2-type T cells, and Type 1 Tregs (Tr1 cells), several studies suggest that IFNγ+IL10+ Th1 cells are a particularly important source of IL10 in human and murine parasitic infections." (PMID 27802341, 2016). "While we found that blockade of these cytokines reduced IFNγ+ cells, there was no change in control of parasitemia." (PMID 26147567, 2015). "Functionally, the failure to produce IFNγ correlated with significantly higher parasitemia, comparable to mice that received no T cells." (PMID 26147567, 2015). "Similar results were observed for total IL-10 and total IFNγ-producing populations, and when assessing the duration since last episode of parasitemia (data not shown)." (PMID 24415936, 2014). "We therefore examined the course of parasitemia in Ifngr1−/− animals as compared to Ifnar1−/−Ifngr1−/− animals in order to assess the function of T1IFNs in the absence of IFNG signaling." (PMID 23144737, 2012). "Thus, lack of activation of macrophages by IFNγ did impact parasitemia in a limited way, but compensatory mechanisms, potentially through TNFα, led to clearance of the parasite." (PMID 39452729, 2024). "Hence, it is possible that as far as the early need for IFNγ is concerned, nu/nu mice have a compensatory mechanism in which the NK/NKT compartment delivers the correct cytokine environment to control early parasitemia by a combination of inflammatory cytokines and T cell independent antibodies." (PMID 32218784, 2020). "Unlike most parasitic infections, such as helminth, which rely on eosinophils, P. falciparum is capable of suppressing eosinophilia, and is characterized by secretion of Th1 cytokines IFNγ and TNF." (PMID 32033605, 2020). "This susceptible phenotype was directly linked to the inability of macrophages to provide a proper anti-VSG response in the absence of IFNγ activation, and their failure to engage in the optimal pro-inflammatory response crucial for the control of early-stage parasitemia." (PMID 32218784, 2020). "A comparable parasitemia count (6h: 8/macrophage and 6/macrophage; 24 h: 13/macrophage and 11/macrophage) between non-stimulated and stimulated cells at both 6 and 24 h was observed showing that IFNγ stimulation has no detrimental effect on the intracellular parasite load." (PMID 35433496, 2022).
parasitemia (continued). "Treatment of CD169DTR mice with diphtheriatoxin (DT) efficiently depleted MMMΦ and MZMΦ, resulting in reduced IFNγ production by CD4+ T cells in P. yoelii-infected mice, though parasitemia progression was not modulated." (PMID 40746561, 2025). "Serum concentration of IL-1α, IL-1β, IFNγ, CXCL10, CXCL9, TNFα in non-infected mice and mice infected with either 1/148 or IL3000, at the first peak of parasitemia (Mean ± SEM; N=3–4)." (PMID 35787830, 2022).
lung carcinoma (380 papers, 1989 to 2026). "In fact, it was recently shown that STK11-mutant lung cancer is associated with interferon gamma signaling in tumors with low infiltration of CD8+ T cells." (PMID 39995872, 2025). "Vaccination with DC pulsed senescent cells resulted in reduction of tumor growth in a CD8+ T cell and interferon gamma-associated manner in lung cancer as well as other tumor models." (PMID 41316207, 2025). "We previously demonstrated a positive association of a TKI-induced interferon gamma (IFNγ) transcriptional response with DOT in EGFR-mutant lung cancers." (PMID 36739466, 2023). "In conclusion, IFNG promoter methylation is associated with decreased IFNG expression in lung cancer patients." (PMID 24244422, 2013). "In conclusion, decreased IFNG expression of CD4+ T cells co-cultured with lung cancer cell is associated with IFNG promoter hypermethylation." (PMID 24244422, 2013). "Using a geneset metascore analysis, we identified immune-related pathways, in particular response to interferon-gamma and antigen processing and presentation, as the pathways that contribute most to our lung cancer risk scores in both current and former smokers." (PMID 38589970, 2024). "Similar results have been observed in other tumor types, such as non–small cell lung cancer, in which PD-L1 expression on ICs was found to be regulated by adaptive IFNγ-mediated mechanisms associated with increased tumor-infiltrating lymphocytes and effector T cells." (PMID 36860696, 2022). "In addition, antigen-presenting neutrophils can be induced in the early stages of lung cancer, an induction that seems to be associated with GM-CSF and IFNγ." (PMID 34204973, 2021). "An IFNγ signature in bulk tumor tissue (which includes a complex mixture of cancer cells, stromal cells and immune cells etc.)has been associated with responsiveness to anti–PD-1 therapy in lung cancer and others malignancies." (PMID 31133614, 2019). "Decreased IFNG serum levels have been linked to shorter survival in lung cancer." (PMID 24244422, 2013). "Lastly, the analysis of gene expression dataset of 186 lung cancer cell lines from Cancer Cell Line Encyclopedia demonstrated that overexpression of PD-L1 was associated with sensitivity to erlotinib and higher expression of genes related to antigen presenting pathways and IFNγ signaling pathway." (PMID 27467256, 2016). "CRTAM–Necl-2 interactions promote cytotoxicity of NK cells and interferon-gamma secretion of CD8+ T cells in lung cancer, thus exerting the immunosurveillance role to distinguish tumors from normal cells." (PMID 41601635, 2026). "Treatment of the human lung cancer cell line A549 in vitro with IFNγ (100 U/mL), a known inducer of LMP7 expression, led to an increased intensity of LMP7 staining with EPR14482(B) by IHC." (PMID 40507366, 2025). "For instance, paclitaxel as well as interferon gamma (IFN-γ) were successfully loaded in hyaluronic acid nanogel, which resulted in enhanced anticancer effects on lung carcinoma A549 cells and alleviated toxic effects on healthy HEK293 cells." (PMID 39996667, 2025). "In the lung cancer patients, they observed differences in interferon-gamma (IFN-γ), interleukin-8 (IL-8), and macrophage inflammatory proteins." (PMID 40313953, 2025). "Meanwhile, it’s confirmed that splenocytes of Ddx21MT immunized mice secreted high IFNγ stimulated by lung cancer cell lines and Ddx21MT peptide." (PMID 39981234, 2025). "On the other hand, studies have shown that OEA and oleic acid decrease PD-L1 expression induced by IFNγ in human lung carcinoma cells." (PMID 38611871, 2024).
lung carcinoma (continued). "IDO1 has been identified as a key marker in the IFNγ signature, as well as other gene signatures predictive of response to ICIs in lung cancer." (PMID 39015091, 2024). "A prime candidate is interferon-gamma (IFN-gamma), a chemokine that has shown capabilities of restoring HLA to HLA-deficient lung cancer." (PMID 39309012, 2024). "For example, it has been reported that CD4+ T cells downregulate IFN-y after activation in lung cancer (we used the hamster lung cancer cell line HT100) through hypermethylation of the IFNG promoter (mechanism of tumour mediated immune suppression)." (PMID 36817448, 2023). "In lung cancer, it can significantly inhibit the proliferation of KRAS mutant lung cancer, downregulate the expression of programmed death-ligand 1 induced by interferon-gamma, and reduce the migration of Lewis lung cancer cells in a CCL2-dependent manner." (PMID 37716981, 2023). "In summary, we demonstrate that IFNγ blockade in capillary leak site prevents drug-induced vascular damages, improves drug delivery and chemotherapeutic efficacy in mouse lung cancer models." (PMID 37056922, 2023). "As a result, it was found that Luteolin and Apigenin dramatically inhibited the growth of lung cancer cells, promoted apoptosis, and decreased the expression of interferon-gamma-(IFN-γ)-induced PD-L1 by suppressing the phosphorylation of STAT3." (PMID 36992138, 2023). "In contrast, we calculated the proteasomal cleavage probabilities of the immune epitopes presented by the lung cancer cell line A549 cells plus/minus treatment with IFNγ." (PMID 37759700, 2023). "First, we investigated in vitro the changes in IDO-1 gene expression (measuring mRNA levels by PCR) induced by IFNγ stimulation, in a panel of lung cancer cells, classified as epithelial or mesenchymal, according previously published EMT score." (PMID 36419183, 2022). "This was consistent with the evidence that more IFNγ release can induce apoptosis of lung cancer cells through activating the JAK-STAT1 pathway." (PMID 36105083, 2022). "Given the compelling evidence that TST treatment reduces overall PD‐L1 protein levels in lung cancer cells in the presence of interferon‐gamma (IFNγ), we investigated the effect of TST on PD‐L1 enrichment in the cell membrane." (PMID 35975458, 2022). "TANs with anti−tumor properties in the early stages of human lung cancer release IFNγ, which stimulates proliferation of T cells." (PMID 34070438, 2021). "When we examined the expression of PD-L1 or PD-L2 on several human lung cancer cell lines before or after stimulation with IFNγ, those expression levels were shown to vary among the cell lines." (PMID 33990697, 2021). "We found that irradiated lung cancer A549 cells were induced dominantly IFNγ in CD8+ T cells, higher than in parental A549 (p < 0.05)." (PMID 34680466, 2021). "The increase in IFNγ secretion from lung carcinomas elicited by pembrolizumab was statistically significant relative to isotype control." (PMID 33597595, 2021). "IFNGR1 and IFNGR2, the cognate receptors of IFNG, were expressed in both monocytes in blood and macrophages in lung cancer." (PMID 35069521, 2021). "We analyzed the endogenous expression of human (h) PD-L1 and hPD-L2 by different human lung cancer cell lines before or after the culture with IFNγ, and found different expression patterns of PD-1 ligands in each lung cancer cell line." (PMID 33990697, 2021). "The TriKE-mediated induction of NK cell degranulation and IFNγ production against lung cancer cells was higher than that seen when NK cells are incubated with K562 targets alone." (PMID 32961861, 2020). "A series of results confirmed that lycopene promoted anti-PD-1 therapeutic efficiency of lung cancer by promoting IFNγ-expressing CD8+ cells infiltrated in tumor tissues and increasing IFNγ expression in tumor cells." (PMID 30948928, 2019).
lung carcinoma (continued). "To that end, we stimulated lung cancer cells, A549, with TNFα and IFNγ and analyzed the changes in both the cellular proteome and HLA presentation." (PMID 30833945, 2019). "Of note, the CD8+FoxP3+ T-cell subset was the only subset able to produce IFNγ after co-culture with autologous lung cancer cells." (PMID 30755279, 2019). "Co-culture with lung cancer cell lines also increased intracellular expression of IFNγ and TNFα in DNT cells, suggesting the activation of these T cells by lung cancer cells." (PMID 30857561, 2019). "Wang et al9 showed that plasma IFNγ levels were significantly decreased in lung cancer patients and hypermethylation of the IFNγ promoter in CD4+ T cells was inversely associated with plasma IFNγ levels." (PMID 30039553, 2018). "PDL2 expression was very low in all four cell lines, and the expression levels increased in the two lung cancer cell lines with IFNγ." (PMID 27631416, 2016). "For this, we treated A549 lung cancer cells with TNFα, IL1β, E. coli lipopolysaccharide (LPS), as well as IFNγ, and assessed secretion of the cytokines CXCL10, IL6 and IL8." (PMID 26030458, 2015). "The result of IFNG promoter methylation of CpG sites demonstrated hypermethylation was similar to that observed in CD4+ T cells of lung cancer patients (85.4% vs 85.4%), which generated lower levels of IFNG upon activation." (PMID 24244422, 2013). "IFNG plays an important role in the tumor host response and decreased IFNG expression is often observed in lung cancer." (PMID 24244422, 2013). "The IFNG levels in lung cancer patients were significantly lower (69.30±38.56 pg/ml) than in healthy controls (92.62±34.75 pg/ml, P = 0.017)." (PMID 24244422, 2013). "In our study, we observed decreased levels of plasma IFNG and intracellular IFNG in CD4+ T cells from lung cancer patients." (PMID 24244422, 2013). "In the current study, we demonstrate that plasma and intra-cellular IFNG levels are significantly lower in lung cancer patients." (PMID 24244422, 2013). "Bisulfite sequence of the IFNG promoter from lung cancer patients (n = 165 clones) revealed a significantly higher degree of methylation at CpG sites relative to those in healthy controls (n = 150 clones)." (PMID 24244422, 2013). "A transwell culturing system was used to investigate the effect of the lung cancer cell line SPC-A1 on IFNG expression of CD4+ T cells." (PMID 24244422, 2013). "Methylation at CpG sites of the IFNG promoter in CD4+ T cells of lung cancer patients and healthy controls." (PMID 24244422, 2013). "A lower frequency of IFNG producing CD4+ T cells were detected in lung cancer patients compared with healthy controls (P<0.001)." (PMID 24244422, 2013). "The present study was set out to investigate effects of IFNγ on the release of the potent pro-angiogenic mediator IL-8 by human A549 lung carcinoma cells." (PMID 18801189, 2008). "Epitope spread responses were measured by IFNγ ELISpot after short in vitro stimulation with a mixture of HLA class II-binding epitopes derived from various TAAs expressed in lung cancer, such as NY-ESO-1, KK-LC-1, mesothelin, and mK-RAS, and with HLA class I peptides from hTERT." (PMID 40543509, 2025). "In lung cancer cells treated with IFNG, both transcription and secretion of HMGB1 are increased." (PMID 39945555, 2025). "In addition, exposure of lung cancer cells to IL-4 suppressed the increase in TAP2 protein induced by IFNγ or IFNγ + TNFα." (PMID 40091029, 2025). "In contrast, previous studies reported that IFNγ could induce UPR to facilitate apoptosis in lung cancer cells or in conjunctival goblet cells, but the molecular mechanism by which UPR is activated by IFNγ has not been revealed." (PMID 40645933, 2025). "Moreover, the transcriptional upregulation of IFN response genes in KPAR cells treated in vitro with IFNγ or IFNα was greatly potentiated by MEKi treatment, validating previous results in other lung cancer models." (PMID 38635884, 2024).